NECTIN3 (nectin cell adhesion molecule 3)
Diseases named in the same sentence as NECTIN3 in open-access papers (continued):
Sharing a sentence is not in itself a finding about the gene and the disease.
tumor (34 papers, 2011 to 2026). "In those studies, reduced nectin-3 expression was associated with higher malignancy, poorer prognosis, and adverse clinical features such as larger tumor size, metastases, and shorter progression-free survival." (PMID 37958883, 2023). "Loss of Nectin-3 expression in PanNETs was associated with larger tumor size, a higher grade, lymphatic involvement, a higher Ki67 labeling index, an advanced pT-factor, lymph node metastasis, an advanced tumor stage, nonfunctioning tumors, and shorter disease-free survival." (PMID 36553083, 2022). "In addition, nectin-3, a cell adhesion molecule that regulates the formation of tight junctions, was revealed as having an inverse association with tumor aggressiveness of pNENs." (PMID 36556070, 2022). "Our results revealed that diffuse nectin-3 expression was associated with a good prognosis, a higher score for nectin-2 was related to a poorer histological grade and a higher score for nectin-4 was related to a larger tumor size." (PMID 25690753, 2015). "TIGIT ligands (PVR, NECTIN2, NECTIN3) were predominantly expressed on tumor cells, while LAG3 ligands (H2-AB1, H2-AA, H2-EB1) were mainly expressed on macrophages and DCs." (PMID 40027748, 2025). "The available literature on nectin-3 in neoplastic diseases is inconsistent and is very limited in the matter of CRC patients." (PMID 37958883, 2023). "Correlation analysis demonstrated a relationship between nectin-3 expression, tumor size, and preoperative CEA levels." (PMID 37958883, 2023). "We also described a putative interaction between FP tumour cells expressing NECTIN3 and the TIGIT receptor on Tregs and NK cells, which was supported by immunofluorescence staining of patient tissue samples." (PMID 37244912, 2023). "We also identify a putative interaction between NECTIN3 and TIGIT, specific to the more aggressive fusion-positive (FP) RMS subtype, as a potential cause of tumour-induced T-cell dysfunction." (PMID 37244912, 2023). "The specificity of this interaction was due to the significantly higher expression of NECTIN3 in FP tumour cells, while the expression of TIGIT in Tregs and CD8 + T cells was comparable between subtypes." (PMID 37244912, 2023). "Interactions between TIGIT and several ligands, including NECTIN3, have been shown to suppress anti-tumour immune responses through several mechanisms." (PMID 37244912, 2023). "The potential role of nectin-3 as a tumor suppressor molecule and its influence on cell junction formation have been highlighted in these studies." (PMID 37958883, 2023). "This analysis highlighted a putative interaction, specific to FP tumours, between NECTIN3 expressed on malignant cells and the TIGIT receptor on Tregs and CD8 + T cells." (PMID 37244912, 2023). "The studies cited above unequivocally indicate a relationship between nectin-3 expression and a tumor phenotype with a poorer prognosis." (PMID 37958883, 2023). "Surprisingly patients who showed the membranous expression of Nectin-3 together with e-cadherin co-location had a better overall survival rate than in the case of the separate localization of both molecules within a tumor cell." (PMID 36553083, 2022). "The three nectin and NECL molecular family proteins CD155(PVR), CD112(PVRL2 or Nectin-2), and CD113 (Nectin-3), which are expressed on tumor cells or antigen-presenting cells, are the known TIGIT ligands." (PMID 36135216, 2022). "In the multivariate analysis, the score of nectin-3 (p = 0.015; hazard ratio 0.360; 95 % confidence interval 0.158–0.832) and tumor size (p = 0.014; hazard ratio 0.429; 95 % confidence interval 0.219–0.841) emerged as independent prognostic factors." (PMID 25690753, 2015). "Further investigation showed that tumour cells had reduced staining of the cytoplasm but concentrated complexes of Nectin-3 within the nuclear area." (PMID 24386110, 2013). "In vivo tumour growth assays showed that Nectin-3 over-expression was able to significantly reduced tumour growth over 28 days, p<0.05." (PMID 24386110, 2013).
tumor (continued). "The engagement of TIGIT by NECTIN3 on tumor cells results in the functional impairment of both T cell subsets, thereby reducing their ability to mount an effective anti-tumor response and promoting tumor immune evasion." (PMID 41007114, 2025). "In multivariate analysis, nectin-3 score and tumor size were independent prognostic factors." (PMID 37568798, 2023). "The role of nectin-3 in processes related to cancer progression, such as invasion, metastasis formation, and prognosis, seems to vary depending on the histological type and origin of the tumor." (PMID 37958883, 2023). "However, Nectin-3 was much reduced in tumour tissues, when compared to background." (PMID 24386110, 2013). "It binds several nectin/nectin-like ligands, including PVR (CD155), PVRL2 (CD112), PVRL3 (Nectin-3, CD113), and PVRL4 (Nectin-4), all commonly expressed by tumor cells and APCs." (PMID 41486149, 2026). "As an IC receptor within the IgSF, TIGIT interacts with ligands such as CD155 (PVR or Nectin-5), CD113 (PVRL3 or Nectin-3), CD112 (PVRL2 or Nectin-2) and PVRL4 (Nectin-4) to suppress T cell activity, facilitating tumour evasion of immune surveillance." (PMID 40994140, 2025). "This means that as the concentration of CEA increased, and as the diameter of the tumor measured in cm and the CRC stage of advancement increased, the expression of nectin-3 decreased." (PMID 37958883, 2023). "As observed in the study group, with an increase in tumor dimension and CEA levels, nectin-3 expression decreased." (PMID 37958883, 2023). "Supporting this finding, IF microscopy on primary tumour tissue revealed the presence of TIGIT-positive cells in both subtypes, while a consistently more prevalent staining pattern of NECTIN3 was observed in FP RMS." (PMID 37244912, 2023). "In contrast, nectin-3 expression negatively correlated with CEA levels, tumor size, presence of distant metastases, and disease stage." (PMID 37958883, 2023). "NECTIN1 and NECTIN4 are most strongly expressed in tumor cells, but NECTIN2 and NECTIN3 are also expressed in some lymphocyte cell types, while TIGIT is largely expressed in Tregs and exhausted CD4+ T cells." (PMID 35995947, 2022). "The interaction pairs via SPP1, RARRES2, NECTIN3, LGALS9, and LAMB1 showed increased signaling in the autophagy-high tumor cells, while SEMA3C, PTN, ICAM1, GAS6, and CSF1 showed decreased signaling compared with those in the autophagy-low tumor cells." (PMID 36830707, 2023). "TIGIT acts as an inhibitor receptor when binding to its ligands PVR, nectin-2, and nectin-3 (CD113), all of which are expressed in APCs and a variety of non-hematopoietic cells, including tumor cells." (PMID 35164813, 2022). "TIGIT can bind to the receptors CD155 (poliovirus receptor-PVR), CD112 (PVRL2, nectin-2), and CD113 (Nectin-3) in immune cells, non-immune cells, and tumor cells, resulting in T cell activation and suppression of cytotoxicity." (PMID 34631507, 2021). "Our results demonstrated that a lack of nectin-3 expression and the tumor size were independent prognostic factors." (PMID 25690753, 2015). "In tumours expressing membranous Nectin-3, some did not co-localize with E-cadherin and these patients showed poorer prognosis than other patients for overall survival." (PMID 24386110, 2013). "Available studies on Nectin-3 are not consistent and suggest that the role of Nectin-3 may be dependent on the histopathological type and location of the tumor." (PMID 36553083, 2022). "Thus, the membranous Nectin-3 that does not have a physiological function (the recruitment of E-cadherin) may contribute to increased tumor malignancy." (PMID 36553083, 2022).
cancer (17 papers, 2013 to 2025). A tumor composed of atypical neoplastic, often pleomorphic cells that invade other tissues. "A promising approach could be to compare the properties of cancer cells with induced nectin-3 overexpression and after loss of nectin-3 expression (e.g., using specific siRNAs)." (PMID 37958883, 2023). "The identification of changes in nectin-3 expression in various cancers will provide a foundation for the development of novel anti-cancer therapies that target cellular pathways using nectin-3." (PMID 40244005, 2025). "It is recommended that the study of nectin-3 expression be expanded to encompass additional cancers." (PMID 40244005, 2025). "It is advisable to extend the studies on nectin-3 expression to other cancers to better understand its role and clinical potential." (PMID 40244005, 2025). "TME of RMS is notably immunosuppressive, marked by an abundance of regulatory T cells (Tregs) and the expression of immune checkpoint molecules such as TIGIT, which interact with NECTIN3 on cancer cells, potentially leading to T‐cell dysfunction." (PMID 39658531, 2024). "In breast cancer, nectin-3 expression was reduced in cancers with positive lymph nodes, increasing NPI and grade, but was elevated with increasing TNM (I vs. III)." (PMID 37568798, 2023). "What accounts for such a varied relationship between nectin-3 expression and prognosis in other cancers?" (PMID 37958883, 2023). "TIGIT binds to three ligands, namely CD155 (PVR), CD112 (Nectin-2), and CD113 (Nectin-3), that are expressed on APCs and cancer cells." (PMID 34948104, 2021). "As has been seen, the research results suggest a certain consistency, indicating that nectin-3 may influence the stage of cancer progression and have significant implications for metastasis and patient survival prognosis." (PMID 40244005, 2025). "However, there have been few reports on the roles of nectin-1, nectin-2, and nectin-3 in cancer development and prognosis." (PMID 36059705, 2022). "In cancer cells therefore, aberrant expression of Nectin-3 could lead to the prevention of TJ protein recruitment, lack of formation of TJs and hence loss of cell-cell integrity." (PMID 24386110, 2013). "Also, the expression level of the nectin-3 gene was lower and that of nectin-4 was higher in HCC tissues compared to in normal tissues adjacent to cancer from all patients (p < 0.05)." (PMID 36059705, 2022).
infection (4 papers, 2014 to 2023). The state of being infected such as from the introduction of a foreign agent such as serum, vaccine, antigenic substance or organism. "During infection, it is likely that TcdB first engages NECTIN3 and frizzled proteins to enter and intoxicate the colonic epithelium." (PMID 37850796, 2023). "ADAMTS20, NECTIN3 and WLS were selected to represent non-infection associated genes with higher expression in Holstein cells." (PMID 35061738, 2022).
CNS tumor (1 paper, 2021). "For brain and CNS tumor samples, CADM1, CADM2, NECTIN1, and NECTIN3 were downregulated, whereas NECTIN2 was overexpressed." (PMID 34925438, 2021).
NECTIN3 also shares sentences with these, for which no sentence is quoted: cognitive disorder (3 papers); nasopharyngeal carcinoma (3); cervical cancer (2); depression (2); gastric cancer (2); lung carcinoma (2); psychiatric disorder (2); Achalasia (1); amyloid (1); amyotrophic lateral sclerosis (1); colitis (1); digestive tumours (1); hemangiosarcoma (1); hemoglobinopathy (1); liver cancer (1); neuroblastoma (1); orofacial cleft (1); osteosarcoma (1); pleural cancer (1); thyroid cancer (1); virus infection (1).